EIF3A (eukaryotic translation initiation factor 3 subunit A)
Diseases named in the same sentence as EIF3A in open-access papers (continued):
Sharing a sentence is not in itself a finding about the gene and the disease.
cancer (continued). "In line with our previous investigations, eIF3a correlated with the prognosis and outcome of clinical cancer therapy." (PMID 35187743, 2022). "EIF3A regulates the expression profiles of proteins that contribute to DNA repair, which in turn is involved in response to anti-cancer drugs." (PMID 36118888, 2022). "Eukaryotic initiation factor 3a (EIF3A), a “reader” protein for RNA methylation, has been found to be involved in promoting tumorigenesis in a variety of cancers." (PMID 34923969, 2021). "The expression of EIF3A can influence cancer cell growth, and the malignant phenotype of cancer cells can be reversed by knocking down EIF3A." (PMID 34923969, 2021). "The expression of EIF3A is different from that of other genes, being expressed at a low level in normal tissues, increases significantly in the presence of cancer, and decreases again in high-grade tumours." (PMID 34923969, 2021). "As a key regulator in cancer, eIF3a is expressed at high levels in multiple cancers and is relevant to the sensitivity of DNA damage-induced therapy, such as platinum agents and ionizing radiation." (PMID 34512348, 2021). "One of these eIFs, eIF3a, has been found to overexpress in many human cancers including cancers of the breast, cervix, esophagus, stomach, lung, and bladder, and it was thought to be a proto-oncogene." (PMID 32974334, 2020). "Alterations in eIF3 subunit expression have been reported for many types of cancer cells, such as the overexpression of eIF3A, B, C, H, I, and M, and under-expression of eIF3E and F." (PMID 32030451, 2020). "We examined the role of eIF3a in the cellular response to IR because IR is a common and an important strategy for treating many types of human cancers and is known to cause DSBs." (PMID 32974334, 2020). "eIF3 is composed of 13 subunits in human and among these, five of them have been shown to be overexpressed in different cancer types, namely eIF3A, B, C, D, and E." (PMID 31795417, 2019). "The expression level of EIF3a in 17 cancer types is generated by the TCGA Database, in which the cancer types are color‐coded according to the type of normal organ that the cancer originates from." (PMID 31197975, 2019). "In fact, in some cancer types, there is a correlation between higher eIF3a expression and the metastatic ability." (PMID 31156702, 2019). "Increment of EIF3A in cancer is interesting in the aspects of tumorigenesis because EIF3A has been highlighted as a translational regulator of a specific subset of mRNA transcripts related to cell proliferation." (PMID 31363116, 2019). "Recently, reports on a relationship between EIF3A and cancer have increased, suggesting that its functions related to cancer progression." (PMID 31363116, 2019). "EIF3A has been already identified as an exosome component released from several cancers, including bladder, ovarian, and prostate cancer." (PMID 31363116, 2019). "There are numerous reports implicating altered expression of eIF3a and eIF3b in numerous types of cancer." (PMID 28981723, 2017). "Upregulation of eIF3a, eIF3b, eIF3c, eIF3d, eIF3e, eIF3h, and eIF3i along with reduced levels of eIF3e and eIF3f has been observed in several cancers." (PMID 28083147, 2016). "The eIF3a mRNA and protein expression level in cancer tissues of these patients were firstly evaluated by realtime reverse transcriptase (RT)-PCR and immunohistochemistry (IHC), respectively." (PMID 26213845, 2015). "For instance, high eIF3a levels, which are typical of early cancer stages, increase proliferation (potentially due to low p27kip1 expression) and differentiation, while decreasing migration and invasion (possibly due to high NDRG1 expression)." (PMID 23437357, 2013). "Suppressing endogenous eIF3a expression had been shown to reverse the malignant phenotype of human cancer cells and overexpression of eIF3a had been found in many cancers such as cancers of lung, breast, cervix, stomach, and esophagus." (PMID 24386425, 2013).
cancer (continued). "eIF3a is known to be upregulated in various cancer entities, ranging from breast, cervical, colon, esophageal to lung, and gastric cancers." (PMID 22619676, 2012). "This awareness to a special position of eIF3a among translation initiation factors initiated many studies investigating the role of eIF3a in a multitude of pathways, interactions, and cancer entities where it is intermingled." (PMID 22619676, 2012). "eIF3a was shown to negatively regulate the NER proteins and, therefore, to reduce DNA repair in cancer cells, which leads to increased apoptosis compared to cells with reduced eIF3a." (PMID 22619676, 2012). "Currently, upregulation of eIF3a is believed to not involve the whole eIF3 complex suggesting a specific role of eIF3a in cancer development and progression ranging possibly beyond its prime protein synthetic function." (PMID 22619676, 2012). "Recent reports indicated that EIF3A functions in various cancers." (PMID 40055250, 2025). "More and more studies have reported the overexpression of eIF3a in several cancers." (PMID 38275418, 2024). "eIF3a was highly expressed in the peripheral blood and cancer tissue of CRC patients." (PMID 38782896, 2024). "Overall, our studies indicate that the oncogenic function of METTL16 relies on its role in reprogramming mRNA translation in cancer (e.g., HCC) cells, and highlight the therapeutic potential of targeting the METTL16/eIF3a axis and mRNA translation program for cancer treatment." (PMID 38302992, 2024). "The finding that the enforced eIF3a expression transformed the normal intestinal epithelial RIE cells into tumorigenic ones is consistent with previous observations that eIF3a knockdown reverses the malignant phenotype of human cancer cells and eIF3a over-expression transforms mouse fibroblasts." (PMID 39413959, 2024). "Our model for how the HLH motif in EIF3A confers specificity on the translation of specific mRNAs involved in various pathways leading to cell proliferation makes it an intriguing target for treating a wide range of cancers." (PMID 37768948, 2023). "Although this speculation needs to be tested in future studies, our findings here provide essential evidence on translational regulation of metabolism by eIF3a in cancer cell proliferation." (PMID 35595099, 2022). "While its contribution to prognosis was previously shown to be due to its function in suppressing synthesis of DNA damage repair proteins, it remains unclear how eIF3a regulates cancer cell proliferation." (PMID 35595099, 2022). "Furthermore, eIF3a is overexpressed in several types of cancers, indicating a special role in carcinogenesis." (PMID 35187743, 2022). "Our findings suggest that glucose metabolism in and proliferation of cancer cells may be translationally regulated via a novel eIF3a–Rheb–AMPK signaling axis." (PMID 35595099, 2022). "eIF3a overexpression can drive cancer cell proliferation but contributes to better prognosis." (PMID 35595099, 2022). "Accumulating studies have reported eIF3a overexpression in several types of cancers." (PMID 35300416, 2022). "We show that eIF3a upregulates AMPK activity and glucose metabolism possibly by controlling Rheb protein synthesis, which may mediate eIF3a regulation of cancer cell proliferation." (PMID 35595099, 2022). "First, we used TIMER to assess the expression of EIF3A in different cancer types." (PMID 34923969, 2021). "EIF3A is a highly conserved gene that may also be involved in the regulation of cellular, physiological, and pathological processes, not only in cancer." (PMID 34923969, 2021). "Moreover, many studies have suggested that eIF3a affects patient prognosis and treatment responses; for example, patients with cancer presenting high eIF3a levels experience better relapse-free and overall survival than those with low eIF3a expression." (PMID 34512348, 2021).
cancer (continued). "Indeed, knocking down eIF3a expression reversed the malignant phenotype of human cancer cells while overexpressing ectopic eIF3a transformed NIH3T3 fibroblast cells in vitro." (PMID 32974334, 2020). "Both eIF3a and eIF3c have been found to be overexpressed in various cancers." (PMID 33148274, 2020). "eIF3a is also a potential oncogene involved in cancer occurrence, metastasis and therapy response." (PMID 32708122, 2020). "As the largest subunit, eIF3a has vital biological functions in various carcinomas, including BC." (PMID 32368187, 2020). "Levels of nine eIF3 subunits involving eIF3A, eIF3B, eIF3C, eIF3D, eIF3E, eIF3H, eIF3I, eIF3J, and eIF3M were significantly increased in cancer tissues, whereas the eIF3L expression level in tumours was independently decreased than that of normal tissues (p < 0.05)." (PMID 31885740, 2019). "The elevation of EIF3A48–53 or its localization in exosome were also reported in several other cancers, which suggests that anti-EIF3A autoantibody biomarker may be induced in other tumors." (PMID 31363116, 2019). "It now seems to be premature to define anti-EIF3A autoantibody as early stage cancer biomarker because of the limitation in clinical samples for retrospective or prospective studies; however, further studies on large, well-defined cohort will show its usefulness for cancer diagnosis." (PMID 31363116, 2019). "Further studies on anti-EIF3A autoantibody as a cancer biomarker in other cancers seem to need, which may expand its use." (PMID 31363116, 2019). "Except EIF3E and EIF3F found down-regulated and conferred tumor suppressive activity in cancers, majority of EIF3 members including EIF3A, EIF3B, EIF3C, EIF3D, EIF3H, EIF3I and EIF3M were up-regulated and played important roles in tumor progression of multiple cancer types." (PMID 29568350, 2018). "Thus, the overexpression of eIF3a, eIF3b, or eIF3c subunits stimulates the expression of other eIF3 subunits that further supports the translational components necessary for faster cancer cell growth." (PMID 28083147, 2016). "Based on this and our previous study, we temporarily speculate that eIF3a maybe also correlated with the chemosensitivity of platinum in patients with other cancers." (PMID 26213845, 2015). "Furthermore, eIF3a also regulates the DNA repair ability of cancer cells and has been reported to influence their sensitivity to chemotherapeutics." (PMID 24586383, 2014). "Taken together, these properties of eIF3a may explain observations that eIF3a over-expression occurs in cancer." (PMID 23437357, 2013). "EIF3a appeared to be essential for cancer cells to maintain malignant phenotype." (PMID 24386425, 2013). "Considering the many cancer entities where eIF3a is already described, this leaves eIF3a as a putative broad-range tumor marker which might still bear important keys for unlocking present issues in cancer diagnostics and therapy." (PMID 22619676, 2012). "However, it remains unknown what regulates eIF3a expression and how its upregulation contributes to both tumorigenesis and cancer cell sensitivity to chemotherapeutics." (PMID 39413959, 2024). "Besides the nucleolar localization, METTL16 also directly associates with eIF3a/b, but not other eIFs, in the cytosol to enhance mRNA translation in cancer cells." (PMID 38302992, 2024). "eIF3a is highly expressed in a variety of cancer types, yet its role in CRC remains unclear." (PMID 38782896, 2024). "Previously, it has been shown that eIF3a has similar functions in promoting tumorigenesis and cancer cell proliferation but contributes to better prognosis by suppressing synthesis of DNA damage repair proteins and promoting cancer cell response to DNA-damaging treatments." (PMID 36997088, 2023). "They together suggested that eIF3a may affect cancer phenotype and therapy by SGs." (PMID 37152897, 2023).
cancer (continued). "Although the eIF3a function in cancer prognosis has been shown to attribute to its function in suppressing synthesis of DNA damage repair proteins in cellular response to DNA-damaging drugs and radiation, it remains to be determined how eIF3a controls cancer cell proliferation." (PMID 35595099, 2022). "Thus, eIF3a upregulation in cancer cells may turn on aerobic glucose metabolism and promote proliferation by activating the Rheb–AMPK pathway." (PMID 35595099, 2022). "In general, high expression of EIF3A being associated with better survival is not consistent with what we recognize as a proto-oncogene, and its mechanisms of action in cancer tumorigenesis and prognosis remain unknown." (PMID 34923969, 2021). "Nevertheless, the findings that eIF3a may suppress the synthesis of DNA repair proteins and contribute to the increased sensitivity of cancer cells to DNA-damaging treatments suggest that eIF3a may be developed as a biomarker for precision medicine prescription." (PMID 32974334, 2020). "In a previous study, we showed that eIF3a knockdown sensitized cancer cells to cisplatin-induced apoptosis, further supporting the conclusion that eIF3a may contribute to cellular sensitivity to DNA-damaging treatments by suppressing DNA repair and by increasing DNA damage-induced apoptosis." (PMID 32974334, 2020). "Moreover, it has been shown that over-expression of eIF3 subunits eIF3a, eIF3b, eIF3c, eIF3i, eIF3h and eIF3m could promote the malignant transformation of various cancers." (PMID 31171919, 2019). "Notably, altered expression levels of many subunits within eIF3–including eIF3a, b, c, e, f, h and m–have been linked to various cancers, although their roles in oncogenesis are not understood." (PMID 24250809, 2013). "Various members of the EIF3 family, such as EIF3A and EIF3D, have been identified as overexpressed in diverse cancer types, including lung, breast, cervix, stomach and esophagus." (PMID 38687509, 2024). "While our results show strong biochemical evidence of EIF3A regulation by MSI2, we acknowledge that the relevance of such a regulation in cancer can only be inferred, and hence a limitation of the study." (PMID 35528200, 2022). "Recent studies have indicated that the upregulation of EIF3A/ B/ C/ H/ I/ M, or downregulation of EIF3E and EIF3F were related to metastasis in several cancers." (PMID 35040374, 2022). "EIF3A also correlated with LINC00662 and LINC01278, which are reported to be involved in many biology functions, such as cell proliferation, carcinoma metastasis, and M2 macrophage polarization via activating Wnt/β-catenin signaling." (PMID 35295989, 2022). "Collectively, we suggest that serum anti-EIF3A autoantibody is a useful biomarker for the diagnosis of HCC and the combinational detection of related biomarkers can enhance the accuracy of the cancer diagnosis." (PMID 31363116, 2019). "However, whether eIF3a also has similar function in other cancers still remains unknown." (PMID 26213845, 2015). "Taken together, the EIF3A HLH motif could be an attractive new target for drug development, both as a novel vulnerability of translationally active cancer cells as well as in combination therapy approaches." (PMID 37768948, 2023). "eIF3a, a 170-kDa protein containing three putative domains including proteasome-COP9-initiating factor 3, spectrin, and the C-terminal 10 amino acid repeat domain, has been shown to overexpress in many types of cancers." (PMID 35595099, 2022). "In addition, G3BP2, WTAP, PCIF1, HNRNPA2B1, EIF3A, and IGF2BP2 were modulated in ≥three cancer types in uncertain manners." (PMID 35211628, 2022). "eIF3a regulation of AMPK and glucose uptake in promoting cancer cell proliferation may work through TBC1D1 and TXNIP regulation of GLUT4 and GLUT1." (PMID 35595099, 2022). "Furthermore, the relationship between eIF3a and PPP2R1B expression was detected in samples from patients with cancer." (PMID 34512348, 2021).
cancer (continued). "The increased expression of eIF3a has been documented in a wide range of cancer cell lines and tumors compared with their non-cancerous counterparts." (PMID 23437357, 2013). "Indeed, several translation initiation factors that are overexpressed in human cancer, including EIF4E, EIF4G, EIF3A, EIF3C, and EIF3H may also contribute to tumorigenesis." (PMID 28594900, 2017). "Finally, for DMRs whose associated genes had increased expression upon treatment with FQI1, we observed enrichment of GO terms for pathways in cancer (e.g. PIAS4, SMAD3, TRAF4, MAP2K1) and RNA transport (e.g. NUP188, EIF3A, NUP35, RAN) in both hyper and hypomethylated DMRs." (PMID 27845898, 2016).